AGT (angiotensinogen)
Diseases named in the same sentence as AGT in open-access papers (continued):
Sharing a sentence is not in itself a finding about the gene and the disease.
Hypertension (continued). "For example, overproduction of adipose‐specific angiotensinogen in mice increased plasma angiotensinogen levels by 30% and could potentially contribute to further hypertension and insulin resistance." (PMID 39247619, 2024). "In conclusion, the genotype distributions of AGT polymorphisms do not influence the risk of developing hypertension in the current study population of isiXhosa-speaking South Africans, and further analysis is needed on a larger sample size." (PMID 38706806, 2024). "IONIS-AGT-LRx is an investigational antisense medicine, conjugated with a ligand, designed to lower angiotensinogen production and thereby reduce blood pressure in patients with treatment-resistant hypertension." (PMID 39062308, 2024). "Fourthly, while the review emphasizes hepatic AGT as the primary therapeutic target, it provides limited information on other emerging targets within the renin–angiotensin system or alternative pathways contributing to hypertension." (PMID 39852196, 2024). "Urinary AGT is increased by hypertension, manifested CKD, IgAN, and DM." (PMID 39273271, 2024). "The AGT rs5051 did not demonstrate any association with hypertension in the present study population." (PMID 38706806, 2024). "Therefore, the aim of this study was to investigate the putative role of AGT gene in hypertension status." (PMID 38706806, 2024). "AGT gene–environment interactions should also be discussed, as they play important roles in the pathophysiology of cardiovascular diseases, such as heart failure and hypertension." (PMID 39852196, 2024). "There is growing evidence that adipose AGT has a potent role in the development of hypertension." (PMID 39125667, 2024). "During diabetes and hypertension, AGT transcription and protein synthesis are augmented." (PMID 38203807, 2024). "RDN at the early stage of hypertension reduced both fat mass and adipocyte size in the present study, and these changes were accompanied by the downregulation of angiotensinogen and ACE gene expression, suggesting that RDN at this stage suppressed RAS-induced adipocyte growth." (PMID 38355818, 2024). "The primary goal of this review article was to determine whether the three RAAS-associated SNPs, Renin-rs16853055, AGT-rs3789678 and ACE-rs4305 are genetically linked to the development of hypertension in preeclampsia." (PMID 38411777, 2024). "In addition, we found genetic polymorphisms of AGT/rs5046, LPR6/rs12823243, and ACE2/rs2285666 were associated with essential hypertension in residents of the cold regions of China." (PMID 39512695, 2024). "In this context, our current study investigated the connection between AGT gene (T704C) polymorphism and specific non-genetic factors with high blood pressure among individuals in Jordan." (PMID 38541014, 2024). "A number of RAAS gene polymorphisms, including those in the aldosterone synthase (CYP11B2), angiotensinogen (AGT), angiotensin II type 1 receptor (AT1R), and angiotensin-converting enzyme (ACE) genes, have been found to be strongly linked to hypertension and ischemic stroke." (PMID 37034069, 2023). "T2DM New Zealand obese mice fed a high-fat diet were used to test a hypothesis that SGLT2 inhibition prevents intrarenal AGT elevation and ameliorates kidney damage and hypertension in T2DM." (PMID 37566054, 2023). "Moreover, IL-6 and TNF-α also promote the production of RAAS components, especially angiotensinogen, further contributing to systemic and local angiotensin II formation and hypertension development." (PMID 37180779, 2023). "The AGT/renin/ACE/Ang II/AT1R axis is responsible for the vasoconstrictive, proliferative, and inflammatory effects whilst its de-regulation is linked to cardiovascular pathology, renal disease and hypertension." (PMID 37308552, 2023).
Hypertension (continued). "The role of AGT on hypertension was strengthened by observations in animal models in which transgenic mice carrying overexpression of a rat angiotensinogen gene develop hypertension, while knockout mice with a disrupted corresponding gene product exhibit normal BP." (PMID 37201134, 2023). "Disruptions in renal function resulting from AGT concentration changes can lead to hypertension." (PMID 37693342, 2023). "Results obtained by immunological staining support the finding in Western blot analysis indicating augmentation of renal cortical AGT protein in Ang II-dependent hypertension (0.81 ± 0.31 in the control group vs. 5.82 ± 2.40 in Ang II-infused group, arbitrary density units, n = 6)." (PMID 35887028, 2022). "In the kidneys of Ang II-infused animals and human renin/human AGT double-transgenic mice, elevated intrarenal angiotensinogen (AGT) expression and urinary AGT levels were observed, supporting an intrarenal Ang II-AGT amplifying mechanism in Ang II-dependent hypertension." (PMID 35887028, 2022). "The plasma concentration of AGT is altered by genetic variations in the AGT gene and may play a part in the development of hypertension, coronary heart disease, and myocardial infarction." (PMID 36557328, 2022). "Our previous work revealed that dimethyl fumarate administration during pregnancy protected adult offspring from the hypertension programmed by prenatal dexamethasone plus a postnatal high-fat diet (which are relevant to the downregulated mRNA expression of renin, angiotensinogen, ACE, and AT1R)." (PMID 35955421, 2022). "Furthermore, the downregulated expression of renal angiotensinogen and the reduced oxidative stress by canagliflozin were found to mitigate high blood pressure and renal tubular fibrosis in mice with T2D." (PMID 36531469, 2022). "Increased angiotensinogen levels led to the suspicion that obese rats developed hypertension with the involvement of the renin–angiotensin system, and this could contribute to the overgrowth of cardiomyocytes." (PMID 33716957, 2021). "Angiotensinogen is involved in hypertension as a precursor of angiotensin II." (PMID 34515626, 2021). "Taken together, these findings strongly imply a modulatory mechanism with the deduction being that episodic hypertension could be triggered by the oxidative conversion of angiotensinogen to its more active bridged form." (PMID 33816576, 2021). "In addition, the unbalanced angiotensinogen affects vasoconstriction and sodium reabsorption and, therefore, increases BP and develops hypertension." (PMID 34046436, 2021). "However, the interactive roles for TNF‐α and intrarenal AGT formation in the pathophysiology of hypertension induced by HS intake, particularly in its non‐dipping blood pressure pattern, are not yet clearly understood." (PMID 34427402, 2021). "The risk allele of rs2004776 binds HNF3β more strongly than does the non-risk allele, increasing angiotensinogen expression and thereby aggravating hypertension." (PMID 33919522, 2021). "Third, the high level of thromboxane A2 (TXA2), plasminogen activator inhibitor-1 (PAI-1), inflammation factors (IF), free-fatty acids (FFA), and angiotensinogen (AGT) may be related to hypertension." (PMID 35186858, 2021). "While we considered the top 10 pathways common between hypertension and COVID-19 using these common 13 and f4-gene sets, we observed that the renin-angiotensin system, metabolism of angiotensinogen to angiotensin, and peptide hormone metabolism pathways were the top pathways for these shared genes." (PMID 34067609, 2021). "Angiotensinogen is involved in hypertension as a precursor of AngII." (PMID 33672844, 2021). "Pathophysiologic mechanisms of hypertension among African Americans may involve the intra-renal renin-angiotensin system, variations in angiotensinogen, and increased aldosterone sensitivity." (PMID 34589710, 2021). "Therefore, AGT affects the key biological function used by Benazepril to treat hypertensive disease." (PMID 33741907, 2021).
Hypertension (continued). "If we could reliably differentiate between the two redox forms of angiotensinogen this could represent a useful biomarker by which to monitor the progression of hypertensive disorders." (PMID 34424335, 2021). "Dietary interventions to increase antioxidant intake could be an acceptable and relatively cheap means of lowering the oxidation of AGT, so reducing or removing this pathway towards hypertension." (PMID 32029819, 2020). "In obesity, the renin-angiotensin-aldosterone system may take on more importance since adipose cells can produce angiotensinogen, and overexpression of angiotensinogen in adipose tissue can contribute to hypertension and adipose tissue development." (PMID 32982794, 2020). "Since renin enzymatic activity is species-specific, a transgenic model of hypertension due to insertion of the human angiotensinogen (AGT) gene in Sprague Dawley rats allowed for characterizing the contribution of a non-renin dependent mechanism for Ang II actions in their blood and heart tissue." (PMID 31803758, 2019). "Therefore, our study aimed to establish the role of polymorphism in the angiotensin-converting enzyme (ACE) and angiotensinogen (AGT) genes in the mechanisms behind the development of oxidative stress in patients with concomitant COPD and hypertension." (PMID 32025262, 2019). "Effects of AGT ASOs on reducing hypertension have been studied in multiple animal models." (PMID 30530571, 2019). "Since postnatal HF diet resulted in higher systemic ANG peptides and AGT in adipose tissue, ACE inhibitors and ANG II receptor blockers may be more suitable treatments for HF diet associated hypertension." (PMID 29540174, 2018). "Though the AGT M235T polymorphism has been complicated in the pathogenesis of arterial hypertension, it has not been associated with hypertension in T1DM and T2DM patients." (PMID 29484134, 2018). "Indeed, several clinical studies have shown that urinary angiotensinogen levels are significantly correlated with albuminuria in patients with hypertension and CKD." (PMID 29600408, 2018). "Furthermore, APOE, NOS3, ACE, AGT, and CYP variants influence the therapeutic response to hypotensive drugs in AD patients with hypertension." (PMID 29301387, 2018). "The aim of the present cross-sectional study was to investigate if polymorphisms of the RAS genes AGT, AGTR1, and ACE might be associated with an increased risk for higher blood pressure and hypertension in the Lithuanian children population." (PMID 28903744, 2017). "Although many studies have reported sex differences in RAS components due to female protection from the development of hypertension and related end-organ damage, the effects of sex hormones on liver and systemic AGT regulation remain unclear and divergent." (PMID 28572913, 2017). "He further performed association analysis with individual SNPs and haplotype blocks and found a positive association with several SNPs in AGT gene with hypertension, though there was no transmission distortion of any particular haplotype for AGT." (PMID 28361007, 2017). "Taken together, these data suggest that nephron‐derived AGT may be involved in Ang‐II‐dependent hypertension, however, a clear role for nephron‐derived AGT in physiological BP regulation remains to be determined." (PMID 26755736, 2016). "Thus, the aim of this study was to evaluate the relation between the RAS genes polymorphisms (AGT 235M/T, ACE I/D, and AT1R 1166A/C) and the essential hypertension in the population of Burkina Faso and to determine hypertension main risk factors." (PMID 26351579, 2015). "These interaction models and epistasis networks amongst AGT, ACE, and AT1R genes may be regarded as potential biomarkers for hypertension susceptibility." (PMID 25961019, 2015).
Hypertension (continued). "In multilocus haplotype analysis, the association between frequencies of the haplotypes and AF risk was showed in AGT gene (rs7539020-rs3789678), compared ‘TT’ haplotype with the common ‘TC’ haplotype, adjusted for age, gender, LVEF, LVEDD, LAD and frequency of hypertension and diabetes." (PMID 25723521, 2015). "Among them, SNP I/D of ACE has the main association effect to hypertension and it also displays n-order interaction effect to SNPs of AGT and AT1R genes although they do not have a mutual effect on each other." (PMID 25961019, 2015). "In addition, the fact that urinary AGT/Cr was higher in the patients with hypertension compared to normotensive patients clearly show that urinary AGT/Cr can be a meaningful biomarker that reflects underlying pathophysiology of ADPKD." (PMID 26092580, 2015). "AGT gene encoding angiotensinogen and ACE gene encoding angiotensin-converting enzyme were investigated most extensively and have been shown to be associated with hypertension." (PMID 25313554, 2014). "On the other hand, adipocyte-specific deficiency of angiotensinogen prevented the obesity-induced increase in plasma levels of Ang II indicating an important role of adipocytes on the regulation of Ang II plasma levels and on ulterior consequences including hypertension and vascular remodeling." (PMID 24600438, 2014). "The M235T variant of the AGT is significantly associated with female hypertensives and ACE DD variant could be a risk allele for essential hypertension in south India." (PMID 24860821, 2014). "Furthermore, dysfunctional adipose tissue produces angiotensinogen and angiotensin II, which induces systemic hypertension." (PMID 23446214, 2013). "In addition, overexpression of the AGT gene in transgenic mice generated by injecting the entire rat angiotensinogen gene into the germline of NMRI mice led to the development of hypertension." (PMID 23894329, 2013). "Meanwhile, it has been reported that the interaction of CYP11B2, angiotensin II type 1 receptors, and angiotensinogen could influence the development of renal insufficiency in essential hypertension." (PMID 23950878, 2013). "Variants in the angiotensinogen gene are associated with hypertension in whites, but not in African-Americans or Yorubas." (PMID 22615923, 2012). "Furthermore, several studies have highlighted a contribution of adipose tissue-derived angiotensinogen and/or angiotensin II to obesity-related hypertension." (PMID 21410966, 2011). "In our data set the M235T SNP in the AGT gene or the ID polymorphism in the ACE gene did not significantly associate with the blood pressure/hypertension phenotype." (PMID 20525211, 2010). "Furthermore, rat Chymase or Rat Mast Cell Protease-II (RMCP-II), which is increased in the serum and mesenteric lymph nodes in portal hypertensive-rats, is able to convert Angiotensinogen into Angiotensin-II (Ang II)." (PMID 18271959, 2008). "Furthermore, a latitudinal cline was identified both for the allele frequencies of the SNPs associated with hypertension (CYP3A5, AGT, GNB3), as well as for those associated with the ability to taste phenylthiocarbamide (TAS2R38)." (PMID 18248681, 2008). "Previous studies have focused on the association of any of the ACE, AT1R and AGT gene polymorphisms with coronary events of several degrees, related or not with MI and essential hypertension." (PMID 18637188, 2008). "Hypertension risks estimates for AGT and ACE genotypes by gender." (PMID 15642127, 2005). "Genes encoding components of RAS, including angiotensinogen (AGT), angiotensin-converting enzyme (ACE), angiotensinogen II type-1 receptor (AGTR1), and renin, have been extensively investigated as genetic determinants of essential hypertension." (PMID 15642127, 2005).
Hypertension (continued). "In hypertension management, examining the role of newer agents including aldosterone synthase inhibitors and injectable angiotensinogen inhibitors which are on the horizon and how the diffusion of such therapies may influence AF-related stroke and mortality is needed." (PMID 41451116, 2026). "Therefore, inhibiting the production of AGT in theliver could be a promising treatment for hypertension by decreasing orpotentially eliminating the production of the powerful vasoconstrictor Ang II." (PMID 40351692, 2025). "In the future, clinical guidelines might include AGT genotyping, with other molecular biomarkers, as part of the process for choosing antihypertensive treatment, which could help move toward more personalized treatment for hypertension." (PMID 40248396, 2025). "It is hypothesized that oral contraception may contribute to hypertension through a ‘first-pass’ effect, where oral estrogens induce hepatic production of the renin substrate, angiotensinogen, leading to an increase in angiotensin I which is in turn converted to angiotensin II." (PMID 38846628, 2024). "Furthermore, AGT plays a crucial role in blood pressure regulation, and targeting this molecule may represent a novel therapeutic approach for hypertension." (PMID 37372091, 2023). "Therefore, although renal oxidative stress is a key pathological factor in the late stage of hypertensive kidney injury, the oxidative stress is unlikely to contribute to renal AGT augmentation that occurs during the early stage of Ang II-dependent hypertension." (PMID 35887028, 2022). "Therefore, we started to focus on the function of PVAT-derived AGT in hypertension." (PMID 36457800, 2022). "In fact, the contribution of the altered angiotensinogen gene, ACE gene, or AT1 receptor gene was previously ruled out in a study that analyzed 2.4 million single nucleotide polymorphisms (SNPs) in approximately 300,000 patients with essential hypertension worldwide." (PMID 35163158, 2022). "However, much experimental evidence suggested that some genetic sequence variants in AGT could be related to the development of CVD, hypertension and blood pressure." (PMID 34834033, 2021). "However, renin is endogenously expressed in the brain, and increased brain RAS activity is also reported for inducing moderate hypertension; certain experimental evidence also suggests that AGT expression in the brain and circulating AGT regulation is an independent phenomenon." (PMID 34925551, 2021). "However, high angiotensinogen levels can be a concern for hypertension." (PMID 34198801, 2021). "Additionally, considering its much smaller size versus renin and angiotensinogen, Ang II may gain access to the brain under conditions where the blood-brain barrier is (partially) disrupted, e.g., in hypertension." (PMID 30949864, 2019). "LNPEP is also involved in the final step of conversion of angiotensinogen to angiotensin IV and enhance acquisition, consolidation and recall in animal models of learning and memory; it may have bearing with REMSD-associated hypertension." (PMID 28367113, 2017). "Therefore, human studies and experimental models support the role of AGT in human hypertension." (PMID 27348013, 2016). "Hence, elevated levels of plasma oxidized angiotensinogen may be a contributing factor to hypertension in the setting of pre-eclampsia." (PMID 26312482, 2015). "For example, the SNP G-217A of AGT gene but not the SNPs A-6G and M235T of AGT gene may associate with hypertension in patients from Taiwan." (PMID 25961019, 2015). "Since our findings also revealed increased activation of RAAS, it is possible to speculate that the more severe hypertension observed in VDD+TDF could be explained by the increased mRNA expression of renin, AGT, ACE, and AT1a associated with augmented levels of aldosterone." (PMID 25048368, 2014).